HOTAIR (HOX transcript antisense RNA)
Diseases named in the same sentence as HOTAIR in open-access papers (continued):
Sharing a sentence is not in itself a finding about the gene and the disease.
cancer (continued). "Data has shown that serum HOTAIR levels were higher in patients with oesophageal squamous carcinoma when compared to controls without cancer, and that HOTAIR levels correlate with tumour node metastasis (TNM) stage." (PMID 35052495, 2022). "Another lncRNA being discussed is HOTAIR (HOX transcript antisense RNA); it is known to enhance proliferation, invasion and metastasis in preclinical studies about cancer, and highly expressed in cancer, such as acute myeloid leukemia." (PMID 36291565, 2022). "As miR-200 family determines the epithelial phenotype of cancer cells by targeting the E-cadherin repressors ZEB1 and ZEB2 proteins, our results displays that HOTAIR induces the migration and metastasis of GC cells through miR-200 family, thereby affecting EMT." (PMID 34923813, 2022). "Although HOTAIR has been found to play the role of proto-oncogene in different types of cancer, the function of HOTAIR in stem cells has not been effectively studied, especially in BCSCs." (PMID 36273585, 2022). "In contrast to its effect in cancer cell lines, HOTAIR overexpression does not affect adipose progenitors’ gene expression or proliferation rates." (PMID 36115964, 2022). "In summary, lncRNAs (e.g., HOTAIR, CARMN, and LINC00478) may regulate cancer processes in multiple ways and be used as cancer biomarkers." (PMID 35740618, 2022). "Our mechanistic characterization of HOTAIR and its functional crosstalk with the well-established oncogene YBX1 may additionally serve to facilitate the development of cancer therapies targeting YBX1 through its interaction with HOTAIR." (PMID 34266873, 2021). "HOTAIR acts as a molecular sponge for miR-326 and negatively regulates FUT6 expression, a direct target of miR-326 involved in the modulation of the PI3K/Akt pathway in human cancer." (PMID 33540611, 2021). "Importantly, HOTAIR is part of the proliferative pathway controlled by bromodomain reader proteins, which are therapeutic targets in GBM and other cancers." (PMID 34596120, 2021). "The two cancer promoters, respectively CCND1 and CCND2, were overexpressed in the ovarian cancer samples, their expression is directly correlated with the upregulated level of HOTAIR." (PMID 34207450, 2021). "A number of studies have demonstrated the role of CSC-related miRNAs/lncRNAs such as miR-1976, miR-196a-5p, miR-221, HOTAIR, and GAS5 in EMT, emphasizing on the multifaceted functions of these transcripts in the carcinogenesis and connection between these cancer-related processes." (PMID 34368145, 2021). "Other lncRNAs such as HOTAIR, MALAT1, and GAS5 also show promise as cancer biomarkers." (PMID 33799946, 2021). "Their high specificity allows for the detection of cancer initiation (e.g., SPRY4-IT1), progression (e.g., ATB), metastasis (e.g., LINC00461, CCAT2 and H19) and response to therapy (e.g., MALAT1 or HOTAIR)." (PMID 34072257, 2021). "The correlation between HOTAIR expression and human cancers has been widely reported; however, there is lack of systematic reviews of the prognostic potential of HOTAIR in cancer." (PMID 34367966, 2021). "In this study, by integrating the expression profiles of the GEO datasets GSE45827 and GSE65216, we identified hundreds of differentially expressed lncRNAs, including HOTAIR, ASAP1-IT1, TUG1, and MIAT, which have been reported to be related to cancer by other investigators." (PMID 32352014, 2020). "Indeed, circulating HOTAIR, MALAT1, and MEG3 transcripts were found significantly higher in cancer patients compared to healthy subjects suggesting their potential as diagnostic biomarkers." (PMID 32154165, 2020). "The lncRNAs Xist and HOTAIR interact with the proteins polycomb repressive complex 2 (PRC2) and lysine-specific demethylase 1 (LSD1) to prevent the transcription of target genes, such as HDAC3 and E-cadherin, and regulate cancer metastasis." (PMID 32164712, 2020).
cancer (continued). "There were no changes in cell viability found at the tested concentration of DsiRNA HOTAIR inhibitor, indicating the impact in vasculogenic mimicry inhibition was not due to unspecific effects in cell survival of cancer cells." (PMID 32466537, 2020). "HOTAIR promotes different processes including tumor growth, metastasis, invasion and migration, the epithelial-to mesenchymal-transition (EMT), and stemness via cancer-type specific pathways." (PMID 32117729, 2020). "In hormone-sensitive PCa, AR signaling is regulated by lncRNAs, such as HOTAIR, which represses the degradation of the E3-ubiquintin - AR complex, which induces castration resistant prostate cancer (CRPC) to promote metastasis of cancer cells." (PMID 32164712, 2020). "HOTAIR, a 2.2 kb gene in the HOXC locus, plays a key role in epigenetic regulation in cancer." (PMID 32883200, 2020). "Forced expression of HOTAIR in epithelial cancer cells induces genome-wide Polycomb repression complex 2 (PRC2) to retarget to a more similar pattern of embryonic fibroblasts, leading to gene expression changes, and increase cancer invasion and metastasis." (PMID 32883200, 2020). "We performed preliminary analysis (deep sequencing-based transcriptome analysis) and found that PTCSC3 was down-regulated in LSCC and negatively correlated with HOTAIR (data not shown), which is an oncogenic lncRNA in cancer." (PMID 31171714, 2019). "Another interesting possible mechanistic explanation for the reported downregulation of miR-326 in cancer tissue when compared to healthy controls is the negative regulator long non-coding RNA HOTAIR (lnc-HOTAIR)." (PMID 30845775, 2019). "HOTAIR and UCA1 with multiple roles in drug resistance may offer big opportunities for targeted chemoresistance in cancer therapy." (PMID 31143372, 2019). "Specific cytosine methylation was found in HOTAIR, which promotes metastasis in several cancer types, but no pseudouridylation was yet reported for this lncRNA." (PMID 30654440, 2019). "The lncRNA HOTAIR (HOX Transcript Antisense Intergenic RNA,) is a transcript, antisense to the mammalian HOXC (homeobox transcription factor C) locus, that is largely deregulated in cancer." (PMID 30154449, 2019). "Dysregulation of H19, HOTAIR, and MALAT1 was observed in many types of cancer." (PMID 31827510, 2019). "HOTAIR plays an oncogenic role in UCC, similar to what it does in many other cancer types." (PMID 30813594, 2019). "Moreover, it is well known that high expression of HOTAIR is connected with EMT process, maintaining of cancer initiating cells, and aggressive types of HNSCC." (PMID 30441874, 2018). "HOTAIR, as a negative prognostic factor, has been reported that it correlated with cancer cell apoptosis, invasion and metastasis in several cancer cell lines." (PMID 29391067, 2018). "Aberrant HOTAIR expression was closely related to cancer metastasis and was defined as a negative prognostic factor for patients with malignant tumor." (PMID 30116729, 2018). "Interestingly, when HOTAIR is overexpressed, EMT is induced, and the self-renewal capacity of cancer stem cells is maintained." (PMID 29732012, 2018). "The combination of all three mechanisms promotes cell migration and invasion in cancer cells, While MKL1 may be a vital molecule in HOTAIR-mediated oncogenic signaling." (PMID 29391067, 2018). "We found that HOTAIR was predominantly higher expressed in cancer tissues than adjacent non-cancer tissues." (PMID 29391067, 2018). "Additionally, HOTAIR, MALAT1, H9 and GAS5 have been reported as prognostic markers in the plasma of cancer patients." (PMID 28872613, 2017).
cancer (continued). "A likely lncRNAs profile will include, among others, HOTAIR, MEG3, NEAT1, UCA1, and/or AK126698 in cancer-drugs cisplatinum-based therapies, and the recently proposed GAS5, UCA1, BC087858 and SOX2-OT involved in the gene-target therapies as EGFR-TKIs based oncological treatments." (PMID 28904641, 2017). "HOTAIR expression is significantly increased in HNC and is correlated with cancer progression." (PMID 27802187, 2017). "We found that HOTAIR, H19 and TUG1 almost appeared in all cancer types." (PMID 28076842, 2017). "Moreover, silibinin suppressed the expression of lncRNA HOTAIR and ZFAS1, which are reported to promote several types of cancers." (PMID 29190895, 2017). "In this study, our results show that the expression of HOTAIR is higher in cancer tissues than corresponding noncancerous tissues of RCC patients, and correlated tightly with metastasis." (PMID 28177890, 2017). "Furthermore, silibinin targets long non-coding RNA: HOTAIR and ZFAS1, which are known to play roles as oncogenic factors in various cancers." (PMID 29190895, 2017). "Various lncRNAs, such as ROR, HOTAIR, H19, UCA1, and ARSR, are involved in cancer stemness." (PMID 29299179, 2017). "In general, HOTAIR is a transacting lncRNA that interacts with Polycomb Repressive Complex 2 (PRC2) and lysine-specific demethylase 1 to negatively influence the expression of cancer-related genes." (PMID 28872613, 2017). "For the lncRNA HOTAIR, its up-regulation also predicted the shorter DFS in cancer patients." (PMID 28410241, 2017). "In the colon CSC subpopulation, HOTAIR was discovered to be expressed at a markedly higher level (CD133+CD44+) compared with other non-stem cancer cells." (PMID 29299179, 2017). "Our results indicated that HOTAIR was highly expressed in cancer tissues than in noncancerous tissues." (PMID 28177890, 2017). "Furthermore, using similar methodologies, HOTAIR itself has also been shown to be a direct transcriptional target of HIF, contributing to cancer cell proliferation, migration and invasion in hypoxia." (PMID 26590207, 2016). "HOTAIR targets PRC2 to hundreds of genes involved in the inhibition of cancer progression, and its depletion abrogates the capacity of EZH2 to induce cancer matrix invasion." (PMID 26029238, 2015). "PRC2 and LSD1/CoREST/REST complex play important roles in the epigenetic regulation of gene expression, it is not surprising that HOTAIR is deregulated so many types of cancer." (PMID 26658322, 2015). "However, only 19 long noncoding RNAs from the LncRNADisease were found among the ESCALs, these including several lncRNAs such as HOTAIR, PVT1, H19 and GAS5 that have been reported to be dysregulated in multiple human cancers." (PMID 26158411, 2015). "It has been demonstrated HOTAIR is pervasively overexpressed in most human cancers compared with noncancerous adjacent tissues." (PMID 26172293, 2015). "HOTAIR is also a tumor-specific negative prognostic factor for the survival of cancer patients and can be detected in serum." (PMID 25912306, 2015). "Subsequent to modulation of HOTAIR expression by knockdown or ectopic overexpression, we did not observe the same effects on HOTAIR target genes among the posterior HOXD genes as previously reported for other cancer types." (PMID 25994132, 2015). "MiR-141, unlike HOTAIR, is a suppressor of tumorigenicity, invasiveness, and malignancy in several cancer types." (PMID 25859406, 2015). "For example, HOTAIR and ANRIL act as cancer regulators in carcinogenesis and cancer progression." (PMID 26448942, 2015). "HOTAIR is also involved in the regulation of other signalling pathways, such as the Wnt/β-catenin pathway, and its aberrantly high expression has been shown to trigger EMT and to help cancer cells acquire a stemness phenotype." (PMID 26404381, 2015).
cancer (continued). "A number of lncRNAs, such as HOTAIR, MALAT and H19 were found to be aberrantly expressed in a number of cancers and extensively characterized as important players affecting the hallmark events of carcinogenesis, such as proliferation, apoptosis, and metastasis." (PMID 25954300, 2015). "As a well-recognized lncRNA, HOTAIR primarily serves as a negative prognostic gene in different cancers including GBM." (PMID 26230711, 2015). "Consistent with this hypothesis, several lncRNAs, such asPTENP1, HULC, GAS5, loc285194,HOTAIR as well as HOTTIP, have been identified as miRNA targets in various cancers, which provide further layers of understanding lncRNA regulation during carcinogenesis." (PMID 26710269, 2015). "We show that HOTAIR is an independent prognostic factor for cancer metastasis (HR 3.90, 95%CI: 2.25–6.74) without heterogeneity." (PMID 25157956, 2014). "In addition to HOTAIR, a correlation between alterations in EED1 was also seen across the different cancer types." (PMID 25275300, 2014). "HOTAIR was previously shown to be an oncogene and negative prognostic factor in a variety of cancers." (PMID 24953832, 2014). "HOTAIR (HOX transcript antisense intergenic RNA), an approximately 2.1 kb lincRNA transcribed from the HOXC locus, is known to alter chromatin configuration and promote cancer." (PMID 24971229, 2014). "This analysis showed that HOTAIR was an independent prognostic factor for cancer metastasis (HR 3.90, 95%CI: 2.25–6.74) without heterogeneity but not for cancer recurrence (HR 1.28, 95%CI: 0.18–9.29)." (PMID 25157956, 2014). "Although the precise mechanism is still not known, it is clear that HOTAIR remodels chromatin to promote cancer invasiveness." (PMID 23443164, 2013). "Given its important role in the epigenetic regulation of gene expression, it is not surprising that HOTAIR is deregulated in different types of cancer." (PMID 24103700, 2013). "To investigate whether HOTAIR has a direct functional role in facilitating NSCLC cell migration and invasion, we evaluated cancer cell invasion through Matrigel and migration through a transwell." (PMID 24103700, 2013). "The expression levels of HOTAIR were significantly higher in carcinoma lesions compared to those of non-cancerous lesions (P=0.019)." (PMID 24130837, 2013). "Scattered, HOTAIR-specific staining was observed in the cytoplasm of carcinoma cells in 48 of the 93 cases, whereas no staining was observed in the normal ESCC cells." (PMID 23717443, 2013). "Other ncRNAs have also been described as being involved in cancer cell survival, including PlncRNA-1, GAS5, HOTAIR, and several miRNA genes, which act by controlling apoptosis, the cell cycle, cell proliferation, or viability, through their interactions with intracellular signaling networks." (PMID 23130941, 2012). "In addition, in primary carcinomas, strong expression of both EZH2 and HOTAIR also trends with worse survival." (PMID 23133536, 2012). "However, the differences in the expression level of HOTAIR throughout the four stages of cancer development was not statistically significant (p = 0.38)." (PMID 39725668, 2024). "Research has shown that HOTAIR interacts with epigenetic regulators such as the lysine-specific demethylase 1A (LSD1) and polycomb repressive complex 2 (PRC2) complexes to regulate the epigenetic silencing of several cancer-related genes, including the HOXD gene." (PMID 36980864, 2023). "HOTAIR expression seems to be elevated in cancer tissues compared to paired non-cancerous tissues, and high expression of HOTAIR has been associated with an enhanced proliferation rate, advanced tumor stage, elevated risk of metastasis, and unfavorable prognosis." (PMID 34527584, 2021). "Moreover, several lncRNAs that have been previously reported to be involved in various cancers as PVT1, HOTAIR, NEAT1, and MALAT1 may contribute to cancer development and progression." (PMID 33670447, 2021).
cancer (continued). "Functionally, HOTAIR promotes proliferation and migration in GBC cell lines, correlating positively with the expression of c-Myc and negatively with miRNA-130a, which suggests that this mechanism may participate in cancer progression in GBC patients." (PMID 34575316, 2021). "Downregulation of HOTAIR could inhibit the invasiveness and metastasis of CRC cancer stem cells." (PMID 34368145, 2021). "As a biomarker combination could be more powerful than a single biomarker, we decided to evaluate, in the same EV samples, the expression of other lncRNAs whose expression in tissue impacted prognosis in other cancers studied by our group, including HOTTIP, HOTAIR, HOXA11, and HOTAIRM1." (PMID 32244977, 2020). "At the same time, it was found that the transcription of HOTAIR in HEp-2 and AMC-HN-8 cells changed after being cultured with cis-platinum and paclitaxel and suggesting that the abnormal expression of HOTAIR has a certain significance in drug resistance of cancer cells." (PMID 32848755, 2020). "Moreover, it was reported that HOTAIR could bind PRC2 to reprogram the chromatin state, thereby regulating the expression of hundreds of genes to promote cancer metastasis." (PMID 32650720, 2020). "The top 15 biological processes in the GO and KEGG pathways showed that HOTAIR participates in “GO:0016477~cell migration”, “Hippo signaling pathway”, “Ubiquitin-mediated proteolysis”, and “TGF-beta signaling pathway”, which are correlated with tumorigenesis and cancer metastasis." (PMID 33302562, 2020). "However, even though exosomes are known to promote cancer metastasis, the functional consequence of increased exosome production by HOTAIR was not studied." (PMID 32429062, 2020). "Notably, elevated expression of HOTAIR and prognosis in cancer patients is not particularly affected either by cancer type or even the patients’ genetic background." (PMID 31195674, 2019). "Previous studies showed that HOTAIR could induce genome-wide retargeting of Polycomb repressive complex 2 (PRC2), contribute to altered H3 lysine 27 methylation, and further regulate various downstream genes and promote cancer cell metastasis." (PMID 30867650, 2019). "Therefore, there is considerable evidence that not only is HOTAIR related to cancer proliferation, but that it is also an independent negative prognostic marker in GBM." (PMID 30483476, 2018). "However, the precise mechanism of biological roles of HOTAIR and MKL1 in cancer cells remain unclear." (PMID 29391067, 2018). "Though these initial experiments are indicative of the pro-metastatic properties of HOTAIR the molecular mechanism of how HOTAIR might be involved in EMT and cancer stem cell self renewal might be more complex than thought and further research is undoubtedly required." (PMID 29732012, 2018). "For example, HOTAIR functions as a molecular scaffold to link and target the histone modification complexes PRC2 and LSD1 and then reprograms chromatin states by coupling histone H3K27 methylation and H3K4 demethylation for epigenetic gene silencing to promote cancer metastasis." (PMID 29416704, 2018). "HOTAIR is also a negative prognostic factor in many cancers." (PMID 28177890, 2017). "In addition, aberrant HOTAIR expression has been extensively revealed to correlate with cancer metastasis and is characterized as a negative prognostic factor for cancer patients." (PMID 28293170, 2017). "HOTAIR was highly expressed in cancer tissues than noncancerous tissues (P < 0.05)." (PMID 28177890, 2017). "However, a majority of previous studies about HOTAIR, which has been indicated as a negative prognostic marker, are focused on its role in the cell biology of various cancer cells and little is known about the regulation of HOTAIR in myeloid cells." (PMID 27680332, 2016).